RNU7-21P (RNA, U7 small nuclear 21 pseudogene)
Synonyms: U7.21
Gene: Small nuclear RNA gene on chromosome 9 (132,963,732 to 132,963,793, forward strand). Ensembl gene ENSG00000238558.
Homologues: Orthologues: chimpanzee U7 (98% identical), macaque U7 (97% identical). Paralogues in human: RNU7-61P (90% identical), RNU7-14P (89% identical), RNU7-27P (89% identical), RNU7-1 (87% identical), RNU7-18P (87% identical), RNU7-23P (87% identical), RNU7-25P (87% identical), RNU7-2P (87% identical), RNU7-34P (87% identical), RNU7-3P (87% identical), RNU7-6P (87% identical), RNU7-7P (87% identical), and 143 more.